BRAF (B-Raf proto-oncogene, serine/threonine kinase)
Diseases named in the same sentence as BRAF in open-access papers (continued):
Sharing a sentence is not in itself a finding about the gene and the disease.
melanoma (continued). "MEK pathways are shown to be involved in an enhanced glucose uptake and the metabolic shift in cancer types with an activated BRAF-MAPK pathway by BRAF mutations like those found in melanoma." (PMID 28724379, 2017). "The MAPK signalling pathway is activated in the majority of malignant melanomas with activating mutations of the BRAF oncogene occurring in almost every second case." (PMID 28415756, 2017). "Cancers bearing BRAF mutations represent approximately 8% of all human malignancies, these mutations occurring more frequently in melanomas (40–70%), and thyroid (36–53%), colorectal (5–22%) and low grade serous ovarian (~ 30%) carcinomas." (PMID 29033690, 2017). "The data obtained in vitro were then validated using a cohort of melanoma patients with BRAF mutations, treated with BRAF inhibitors and where PD-L1 expression in the metastatic lesions had been studied." (PMID 28199980, 2017). "The functional significance of upregulation of CD47 by BRAF/MEK inhibitors is revealed by increased susceptibility of melanoma cells resistant to BRAF inhibitors to macrophage phagocytosis when CD47 is inhibited." (PMID 29050218, 2017). "Even though the mutational status was not a consistent risk factor for OS in multivariate analysis, our results suggest that NRAS-mutant tumors tend to behave more aggressively than their BRAF-mutant and WT counterparts in a high-risk melanoma population." (PMID 28797232, 2017). "Novel therapeutic strategies for the treatment of advanced melanoma is the urgent priority all long, especially BRAF V600E mutated melanoma." (PMID 29202777, 2017). "This is exemplified by the recent approval of combined BRAF and MEK inhibition for therapy of patients with metastatic BRAF-mutated malignant melanoma." (PMID 28507280, 2017). "Nearly 15-30% of mucosal melanomas in the head and neck region harbor activating mutations in BRAF and KIT." (PMID 28404968, 2017). "Other BRAF mutations include V600K, V600R and V600M, estimated as being present in 7.8%, 1% and < 1% of melanomas, respectively." (PMID 29100459, 2017). "Nine patients had a BRAF mutated melanoma, of whom six had been treated with a BRAF inhibitor in the metastatic setting." (PMID 29157311, 2017). "Vemurafenib, a targeted kinase inhibitor of the B-Raf protein variant produced by a V600E point mutation in BRAF, has been shown to reduce tumor burden and to improve overall survival in melanoma patients." (PMID 28555425, 2017). "Approximately half of all malignant melanomas harbor an activating mutation in the serine/threonine kinase BRAF; ~90% of these mutations involve a valine to glutamic acid substitution at residue 600 (V600E)." (PMID 28147313, 2017). "Patients with BRAF-mutant melanoma were significantly younger than those with NRAS mutations or WT patients (median 56 versus 66 and 67 years, respectively; p < 0.001)." (PMID 28797232, 2017). "Accordingly, we conducted this study to investigate NRAS Q61 mutations and M%NRAS in a series of 199 melanomas wild type for BRAF V600." (PMID 28668077, 2017). "A total of 138 cases of melanoma samples harboring BRAF V600E mutation were included, and EZH2 copy numbers were examined by QuantiGenePlex DNA Assays." (PMID 29202777, 2017). "We also confirm that melanoma cells expressing BRAF splicing variants retain exquisite sensitivity to existing FDA-approved MEK inhibitors." (PMID 28503307, 2017). "Within the limited data concerning melanoma, ipilimumab given prior to a BRAF inhibitor appears to be more effective in BRAF mutation–positive melanoma." (PMID 29156850, 2017). "We demonstrated the proliferative kinetics of BRAF-mutated melanoma cells treated with the BRAF inhibitor PLX4720 fall along a spectrum of sensitivity, providing a model system to study the interplay of metabolism and drug sensitivity." (PMID 28205616, 2017).
melanoma (continued). "We analyzed BRAF V600E mutated melanomas to explore the Reflectance confocal microscopy (RCM) utility as a screening aid in the evaluation of the most appropriate patients for genetic testing." (PMID 28662062, 2017). "Overall median survival time (MST), stratified for variables, including BRAF V600E mutation and eligibility for treatments with new immunotherapy drugs, was retrospectively assessed in 41 patients with pelvic melanoma loco regional metastases." (PMID 29120401, 2017). "Activating mutations of the v-Raf murine sarcoma viral oncogene homolog B (BRAF) gene occur in up to 50% of melanoma patients, with a higher frequency among very young patients." (PMID 28374234, 2017). "In melanoma, over half of patients are reported to harbor activating mutations in the BRAF oncogene." (PMID 28085880, 2017). "In melanoma disease, approximately 50–60% of tumours contain a mutation in the gene that encodes BRAF that leads to constitutive activation of downstream signaling in the MAP kinase pathway." (PMID 29113311, 2017). "RAF-targeted therapies such as vemurafenib and dabrafenib are approved treatments for malignant melanomas with BRAF-V600E/K mutations." (PMID 29156677, 2017). "Because BRAF acts as a serine/threonine kinase and becomes activated by a somatic point mutation, it plays an important role as a target for drug development in malignant melanoma." (PMID 28718799, 2017). "Mutationally dominant neoplasms, such as BRAF or RAS driven melanomas, are often treated successfully with single agent therapies." (PMID 28714919, 2017). "In a previous study of combined lung cancer, colorectal cancer and melanoma specimens, kinase-impaired BRAF mutants were associated with a higher incidence of a concomitant activating KRAS/NRAS mutation." (PMID 29228562, 2017). "For example feedback activation of EGFR has been shown to cause intrinsic resistance to BRAF inhibition in colon cancer, and resistance to BRAF inhibition in melanoma can be caused by reactivation of the MAPK pathway by RTKs, NRAS, or COT." (PMID 28145866, 2017). "B. Traces showing alternate BRAF splice junctions and the exon 15 Val600 codon (boxed) in BRAF inhibitor progressing melanomas expressing the BRAF exon 4-8Δ splice variant." (PMID 28503307, 2017). "A subgroup of patients with BRAF-mutated melanoma showed limited response to these inhibitors due to intrinsic resistance." (PMID 28265552, 2017). "In the same way, activation of BRAF by mutation in melanoma should lead to the induction of genes involved in antioxidant defence, since MAPK activation was described to induce such a response." (PMID 28595656, 2017). "Somatic mutations in BRAF are found in several kinds of cancers, including melanoma, ovarian carcinomas, colorectal cancers, papillary thyroid cancers, and lung cancers." (PMID 28135039, 2017). "Based on these results, we predicted increasing the rate of glycolysis while depleting glycolytic reserve would decrease the IC50 value for a BRAF-mutated melanoma to PLX4720 treatment." (PMID 28205616, 2017). "More than half of melanomas harbor activating V600E mutation of BRAF (BRAFV600E), a critical driver gene for the proliferation and survival of melanoma cells through the activation of MAPK pathway." (PMID 28632938, 2017). "BRAF is a well-established target in melanoma, where the commonly observed V600E point mutation leads to constitutive BRAF signalling and sensitivity to BRAF inhibitors." (PMID 29225694, 2017). "The five remaining melanomas all harbored MAPK pathway activating mutations in BRAF or NRAS and three had activating mutations in the β-catenin pathway." (PMID 28935960, 2017). "For BRAF-mutated melanoma patients, targeted combination therapy with BRAF and MEK inhibitors is recommended, a treatment line, which has been approved in 2015." (PMID 28595656, 2017).
melanoma (continued). "For example, the type-III MEK kinase inhibitor, Cobimetinib (IC50 0.9 nM), overcomes the resistance induced by the BRAF V600E mutation seen in melanoma by inhibiting MEK, which is downstream of BRAF in the BRAF/MEK/ERK pathway." (PMID 28628649, 2017). "Other great achievements include the identification of the BRAF mutation as driver in malignant melanoma and the development of vermurafenib which targets BRAF-mutant tumors." (PMID 28977985, 2017). "Overall, these results further indicate that LKB1 low levels are negatively linked to MMP-2 high levels in BRAF V600E human melanoma tissues." (PMID 29371951, 2017). "First of all miRNA expression levels were compared between melanocytes and six BRAF-mutated melanoma cell lines through a sensitive microarray profiling platform." (PMID 28118616, 2017). "The present study highlights the potential of RCM to be used as a supplementary tool in the screening for BRAF-mutated melanomas." (PMID 28662062, 2017). "In melanoma, validated drug targets with companion diagnostic utility now include BRAF and c-KIT, as these are driver oncogenes in which activating mutations occur and can be targeted by tyrosine kinase inhibitors (TKIs)." (PMID 28228113, 2017). "In a previous report, we did not observe any significant changes in BAG3 positivity distribution between BRAF WT and BRAF mutated melanoma samples of primary tumours." (PMID 29113311, 2017). "To determine the metabolic profiles exhibited by our panel of BRAF-mutated melanomas, we quantified lactate-producing glycolysis and mitochondrial oxidative metabolism using the Seahorse extracellular flux analyzer platform." (PMID 28205616, 2017). "The development of BRAF-targeted therapies was initiated with the discovery of BRAF-V600E point mutation in melanomas, which emerged to be one of the most prevalent RAF mutation across human cancers." (PMID 29156677, 2017). "Pembrolizumab is a high-affinity humanized PD-1 monoclonal antibody, which in a phase 3 study was compared with ipilimumab treatment in melanoma patients with BRAF V600E mutations." (PMID 28730140, 2017). "Overall, ~20% of all cancers carry driver mutations in one of the genes that encode MAPK pathway proteins and in the case of melanoma, 50% of cancers carry activating point mutations in BRAF (most commonly BRAF V600E)." (PMID 29175850, 2017). "The sample size of the current study was larger than, or comparable to, those of several other studies reporting BRAF mutation rates in melanoma." (PMID 29176861, 2017). "A trial to assess the triple combination of trametinib, dabrafenib, and the anti-programmed death-ligand 1 (PD-L1) antibody durvalumab in 26 patients with BRAF-mutated advanced melanoma was conducted." (PMID 28954413, 2017). "This provides a strong rationale for the clinical development of new targeted therapies focussing on RSK with the ultimate goal of a better and prolonged management of BRAF-mutated advanced melanoma." (PMID 28415756, 2017). "In BRAF mutant melanomas, for example, only 11% of detected resistance mutations were outside the mitogen-activated protein kinase (MAPK) pathway." (PMID 28431544, 2017). "In keeping with published studies, there were frequent mutations of BRAF and NRAS in melanoma; BRAF, EGFR, KRAS, and STK11 in NSCLC; APC, BRAF, KRAS, and PIK3CA in CRC; KIT and PDGFR3A in GIST; and CTNNB1 in other tumours (desmoid fibromatosis)." (PMID 28196074, 2017). "We recently studied the frequency of BRAF mutant alleles (M%BRAF) and showed that M%BRAF is highly heterogeneous and frequently increased in BRAF mutated melanomas." (PMID 28668077, 2017). "Upon combined treatment with the HDACi, SAHA, and the BRAF inhibitor, PLX4720, cell death was strongly induced in BRAF-mutant melanoma cells, while in melanocytes the treatment caused very low toxicity." (PMID 28596940, 2017).
melanoma (continued). "To unravel BRAFi resistance mechanisms we have performed gene expression and mass spectrometry based proteome profiling of the sensitive parental A375 BRAF V600E-mutated human melanoma cell line and of daughter cell lines with induced BRAFi resistance." (PMID 29048432, 2017). "In melanoma, the most common mutation of BRAF is a substitution from valine (V) to glutamic acid (E) in codon 600 of exon 15 (V600E)." (PMID 28797232, 2017). "In the present study, we used a panel of human BRAF-mutated melanoma cell lines to demonstrate in vitro variability in response to PLX4720, a BRAF inhibitor and analogue of vemurafenib." (PMID 28205616, 2017). "Although cancers such as melanoma predominantly have V600 BRAF mutations, non-V600 BRAF mutations are very common in NSCLC." (PMID 28947956, 2017). "Yet, despite a prolonged response to the combined treatment, resistance still develops within the first year of therapy in half of the treated patients and remains a major problem in the management of BRAF-mutated advanced melanoma." (PMID 28415756, 2017). "Clinical trials using various MEK inhibitors, such as trametinib, cobimetinib and CI 1040 (PD184352) have been shown to shrink some melanomas, specifically those with BRAF mutations." (PMID 28187762, 2017). "In this regard, it is worth noting that approximately 50% of melanomas harbor V600E mutation in BRAF, a genetic abnormality that renders the MAPK signaling pathway constitutively active." (PMID 29187213, 2017). "Our results further show that activating MEK mutations that have arisen in melanoma cells with BRAFV600E mutations result in suboptimal melanoma growth following the withdrawal of BRAF inhibition." (PMID 28263969, 2017). "Haq in his papers assessed that BRAFV600E mutation is the most frequent genetic mutation in melanomas and the activation of the BRAF/MAPK decreases the oxidative metabolism." (PMID 27738305, 2017). "TERT promoter mutations occur in melanoma as frequently as, or more frequently than BRAF mutations, and yet mainly BRAF mutant specific cfDNA is being used to monitor melanoma patients for response to therapy and disease progression." (PMID 29108273, 2017). "BRAF mutation frequency ranges from 40 to 60% depending on melanoma clinical characteristics and detection technique used." (PMID 28039443, 2017). "BRAF plus MEK-targeted drugs have outperformed BRAF inhibitor monotherapy in randomized clinical trials on BRAF-mutated melanoma." (PMID 29137342, 2017). "The discovery of sensitizing BRAF mutations in melanoma provided a strong biologic rationale for the development and the rapid implementation of BRAF‐inhibitors into clinical trials." (PMID 28719152, 2017). "The most common BRAF mutation is the substitution of valine for glutamic acid (VAL600Glu or V600E) accounting for approximately 90% of all BRAF mutations seen in melanoma." (PMID 28993799, 2017). "Inhibition of MAP kinase pathways by selective BRAF inhibitors, such as vemurafenib and dabrafenib, have evolved as key therapies of BRAF-mutated melanoma." (PMID 28151482, 2017). "We identified miR-579-3p through the online algorithm miRò, by querying potential miRNA deregulated during melanoma progression in relationship with BRAF mutational status." (PMID 28118616, 2017). "In the following sections we describe the settings and results for a cohort case study in 93 BRAF-wt/RAS-wt melanomas, as an example implementation for variant exploration using CVE." (PMID 28545463, 2017). "Taken together, these results led us to propose that, while CRAF acts as the predominant kinase downstream of NRASQ61K to sustain melanoma growth, its loss can be rapidly compensated by BRAF." (PMID 28497782, 2017). "For example, mutated BRAF is seen in melanomas, ALK raises suspicion for lung cancer, and EGFR has been described in multiple cancer types including lung, colorectal, pancreatic, breast, and thyroid." (PMID 28054963, 2017).
melanoma (continued). "The methods compared here all have the ability to find mutations within melanoma, particularly those in BRAF." (PMID 28228113, 2017). "More than half of melanomas are characterized by an activating BRAF mutation and transiently respond to BRAFV600E inhibitors, but almost all patients develop resistance to these agents and subsequently relapse." (PMID 27974353, 2017). "As an additional mechanism of action, vemurafenib stimulates NO• and O2•− production and it also induces depolarization of mitochondrial membranes in BRAF V600E-mutated melanoma cells, potentially initiating apoptosis and growth inhibition." (PMID 28698765, 2017). "Approximately 50% of melanomas carry a BRAF and 15% an NRAS mutation causing the activation of the mitogen-activated protein kinase (MAPK) pathway." (PMID 28596940, 2017). "Activating BRAF mutations (most commonly BRAFV600E) are found in about 50% of melanomas, and lead to constitutive activation of BRAF and downstream MAPK signaling." (PMID 29137342, 2017). "This is due to the benefit of BRAF inhibitors as a treatment for brain metastases in BRAF mutation positive melanoma." (PMID 28819707, 2017). "In melanomas harbouring BRAF V600E mutations, a BRAF inhibitor induces remission of the tumour; however, the same drug is ineffective in colorectal cancer cells harbouring identical mutations." (PMID 28637487, 2017). "Further, we evaluated the antimetastatic properties of MC3181 in a third tumor cell line, namely the BRAF-V600E-mutated SK-MEL-5 human melanoma cell line, which has been established from an axillary lymph node metastasis." (PMID 28107182, 2017). "In summary, our results demonstrated that LKB1 inactivation plays a cooperative role with BRAF mutation in promoting melanoma cells invasion and migration by activation of PI3K/Akt/mTOR signaling pathway and MMP-2 expression." (PMID 29371951, 2017). "Nearly 60% of melanoma cases have mutations in BRAF (v-raf murine sarcoma viral oncogene homolog B)." (PMID 29276510, 2017). "In vitro, the V600E mutation confers 500-fold higher activity in BRAF than normal and promotes the transformation of melanocytes to melanoma." (PMID 29276510, 2017). "Taken together, these results indicated that when CRAF is knocked down in NRAS-mutated human melanoma cell lines, BRAF is able to compensate to maintain MAPK activation and proliferation." (PMID 28497782, 2017). "MAP2 promoter activity levels in melanoma cell lines have also been found to correlate with activating mutations in BRAF." (PMID 29179510, 2017). "Here, we investigated the role of LKB1 loss in BRAF V600E mutation and BRAF wild type melanoma cells respectively." (PMID 29371951, 2017). "BRAF mutation occurs in up to 66% of human malignant melanomas and for this reason BRAF has been one of the primary targets in melanoma therapy." (PMID 28724377, 2017). "Small molecule inhibitors (such as Vemurafenib also known as PLX4032 or Dabrafenib also known as GSK2118436), which bind with high affinity to the mutated form of BRAF have been successfully used as monotherapy in melanoma patients." (PMID 28595656, 2017). "Taking into account the results published in BRAF mutated melanomas, though unproved on thyroid PTCs, BRAF inhibition also stimulates some gene programs such as oxidative phosphorylation, mitochondrial mechanisms, and the levels of PGC1α." (PMID 27738305, 2017). "About half of melanoma patients have an activating mutation in BRAF, an oncogene involved in the MAPK pathway that is a key regulator of cell growth, division, and differentiation." (PMID 28993799, 2017). "BRAF V600E is the most common mutation found in melanoma; then we analyzed the effect of LKB1 loss on migration and invasion of the melanoma cell lines in the presence of BRAF V600E." (PMID 29371951, 2017).